IL6 (interleukin 6)
Diseases named in the same sentence as IL6 in open-access papers (continued):
Sharing a sentence is not in itself a finding about the gene and the disease.
Sepsis (continued). "Early correlations between NAL and IL-6 and IL-8, dissipating after four hours, highlight the transient nature of inflammatory responses in sepsis." (PMID 40057738, 2025). "Studies have shown that elevated levels of IL-6 and TNF-α are strongly associated with poor outcomes in sepsis patients, highlighting their central role in the pathophysiology of the disease." (PMID 40563999, 2025). "In sepsis, IL-6 levels are markedly elevated, due to its increased production by a variety of immune cells: monocytes, macrophages, and endothelial cells." (PMID 40149943, 2025). "In the validation set GSE209706, the sepsis (LPS-treated) group showed significantly increased levels of Cxcl10, Il6, and Stat1 compared to the control group." (PMID 40792069, 2025). "Previous studies have demonstrated significant associations between elevated IL-6 levels and increased mortality or risk of MOD in patients with critical illness, including sepsis." (PMID 39800741, 2025). "Interleukin-6 (IL-6) is a cytokine that predicts clinical outcomes in critically ill patients, including those with sepsis." (PMID 39800741, 2025). "Compared to other antibody treatments, very low amount of sgp130 is required to prevent fatal sepsis in mice, underscoring the merit of blocking of IL-6 trans-signaling." (PMID 40114923, 2025). "The pathological expansion of MDSCs in sepsis is driven by sustained production of inflammatory factors like IL-6 and TNF-α, and the activation of signaling pathways such as STAT3 and NF-κB." (PMID 40364841, 2025). "MALAT1 depletion is responsible for the sepsis inflammatory response by inhibiting the expressions of IL-6 and TNF-α and the NF-κB signaling pathway by upregulating miR-150-5p." (PMID 40041174, 2025). "In the multivariate linear regression, IL-6 was the only predictor of sepsis (p-value < 0.05), as confirmed in a multiple quantile regression." (PMID 40732663, 2025). "For example, IL-6 plays a critical role in the acute phase response, but its overproduction during sepsis can lead to endothelial dysfunction, vascular leakage, and hypotension, contributing to septic shock." (PMID 40563999, 2025). "IL-6, an important biomarker of sepsis, has a level closely correlated with the severity of the disease." (PMID 40072101, 2025). "In vitro, miR-130b-3p inhibited eCIRP-mediated release of TNF-α and IL-6 from macrophages and was beneficial in attenuating inflammation and organ injury in polymicrobial sepsis." (PMID 39838468, 2025). "Using the “irGSEA” package, we scored hallmark pathways: Macro_1_FCGR3A showed downregulation of IL6-JAK-STAT3 but upregulation of PI3K-AKT-mTOR and TNF-NFκB signaling, suggesting an anti‐sepsis role." (PMID 41332909, 2025). "SAA and Cxcl1/KC were reported to promote the mobilization of myeloid-derived suppressor cells cooperatively by a pathway dependent on hepatic IL-6-gp130-STAT3 signaling in the liver during sepsis." (PMID 40429677, 2025). "Sepsis is a critical illness caused by infection that leads to excessive activation of systemic inflammatory cytokines, such as TNF-α, IL-1β, and IL-6, inducing immune dysfunction and resulting in systemic organ failure." (PMID 40565375, 2025). "The repeated failure of cytokine-targeted therapies such as anti-TNF, anti-IL-1, and anti-IL-6 antibodies in sepsis reflects systemic issues in trial design and patient selection rather than the absence of biologic relevance." (PMID 41268545, 2025). "This immunomodulatory effect of DEX was also observed in a CLP mouse model, in which DEX-treated sepsis mice had significantly lower concentrations of IL-6 and IL-1β in the blood and hippocampus." (PMID 41124072, 2025). "The hyperinflammatory phase in sepsis is characterized by the excessive and uncontrolled release of pro-inflammatory cytokines, such as interleukin-6 (IL-6) and tumor necrosis factor-alpha (TNF-α)." (PMID 40563999, 2025).
Sepsis (continued). "Studies in sepsis models revealed that TREM-1 knockout mice express lower levels of IL-6, TNFα, and IL-1β compared to wild-type mice after eCIRP injection." (PMID 40332009, 2025). "This systematic review and meta-analysis sought to clarify the prognostic value of interleukin-6 (IL6) in predicting mortality among critically ill patients with sepsis." (PMID 40149943, 2025). "On the other hand, values of PCT, IL-6, presepsin, and endocan were significantly higher for neonates with sepsis." (PMID 40506913, 2025). "IL-6 and MMP-9 expression activate host defense mechanisms, which have been linked to increased inflammation and vascular permeability and serve as sepsis biomarkers." (PMID 40565223, 2025). "While few studies have specifically examined β-blockers’ impact on postoperative sepsis risk, existing evidence indicates that early β-blocker use might exert anti-inflammatory effects by reducing circulating inflammatory proteins and suppressing pro-inflammatory cytokines like IL-6." (PMID 40808690, 2025). "Up to our knowledge, the stronger effect on the gene expression of the pro-inflammatory cytokines IL-1b and IL-6 through ASCs compared to BMMSCs at the early (8 h) onset of sepsis is a new finding." (PMID 40253667, 2025). "Although CRP, PCT, and IL-6 are all established biomarkers in the diagnosis and management of sepsis, our study was limited by the availability of complete PCT and IL-6 data for all patients in our cohort." (PMID 40568199, 2025). "IL-6 is a pro-inflammatory cytokine that plays an important role in innate immunity and is upregulated in sepsis, after trauma, and medical treatment, e.g. surgery." (PMID 40114261, 2025). "The data from our initial study indicate that IL-6 exhibited an upward trend in the early stages of sepsis and reached a peak during this initial phase, followed by a decline to a low and stable level." (PMID 39955435, 2025). "Sepsis induces endothelial cell activation and dysfunction, driven by pro-inflammatory cytokines such as interleukin-6 and tumor necrosis factor-alpha." (PMID 39821561, 2025). "IL-6 exhibits marked temporal dynamics during sepsis, with levels typically peaking within 24 h of infection onset and declining with effective treatment or progressing to persistently elevated levels in patients developing multi-organ failure." (PMID 41439926, 2025). "The sepsis control group demonstrated a significant increase in IL-6 concentrations over time, with higher levels observed at the 10th hour." (PMID 40566580, 2025). "While IL-6 serves as an early alarm for systemic inflammation, its non-specificity restricts its utility as an isolated biomarker of sepsis in thoracic surgery." (PMID 41281040, 2025). "While high IL-6 values were observed in the early hours of sepsis, IL-6 levels decreased in the late period of sepsis." (PMID 39955435, 2025). "This study contributes to our understanding of the potential impact of laminarin on IL‐6 levels in sepsis." (PMID 40045157, 2025). "With a lower cut-off of 40.5 pg/mL, IL-6 yielded 92.3% sensitivity, 90.5% specificity, and an AUC of 0.959, far surpassing conventional sepsis screening markers such as CRP, total leukocyte count and absolute neutrophil count." (PMID 41302151, 2025). "Material and Methods: We analyzed recent clinical and experimental studies focusing on the most studied ILs—including IL-1, IL-6, IL-10, IL-8, IL-12, IL-18, and IL-17—in the pathophysiology of sepsis." (PMID 41300951, 2025). "During the sepsis process, IL-6 was observed at high levels between the 2nd and 6th hours, and a decrease in IL-6 levels began to occur from the 8th hour." (PMID 39955435, 2025). "The level of IL-6 in umbilical cord blood is the only predictor of early-onset sepsis and can be used to predict NS in the hours after birth." (PMID 39886481, 2025). "Mitochondrial transplantation conducted one hour after CLP showed a tendency towards reducing TNF-α, IL-1β, and IL-6 levels compared to the Sepsis group." (PMID 40584438, 2025).
Sepsis (continued). "Given these biological functions, IL-6 has been extensively investigated as a prognostic biomarker in sepsis." (PMID 41300951, 2025). "After logistic regression, it was found that RDW, APACHE II score, PCT, IL-6, CRP, and cystatin C were all independent risk factors for AKI in children with sepsis (P<0.05)." (PMID 41281283, 2025). "In these patients, serial measurements of GLP-1 and IL-6 were obtained, revealing that elevated GLP-1 concentrations within the first 24 h of sepsis onset were strongly associated with early mortality and the development of chronic critical illness." (PMID 41357527, 2025). "The proinflammatory cytokines, including TNF, IL-1, and IL-6, have been identified as potential mediators of the metabolic disturbances in sepsis." (PMID 39838305, 2025). "In our polymicrobial sepsis model, at 2 hours post-infection, we found that fluoxetine-pretreated mice had equivalent induction of TNFα and IL-6 and significantly higher levels of serum IL-1β compared to vehicle-treated infected mice." (PMID 39951524, 2025). "Cxcl10, Il6, and Stat1 showed higher levels of expression in the sepsis group than in the control group in the RNA-seq data (P < 0.05)." (PMID 40792069, 2025). "GSK-J4 has demonstrated anti-inflammatory efficacy in various preclinical models, including colitis, arthritis, and sepsis, by downregulating IL-6, IL-17, and TNF-α, as well as attenuating inflammasome activation." (PMID 40801194, 2025). "IL-6 reached peak concentrations in the early stages of sepsis, whereas lung damage peaked subsequent to the IL-6 peak, and kidney damage manifested considerably later." (PMID 39955435, 2025). "Sepsis led to an increase in the expression of IL-6, TNF-α, and a decrease in the expression of occludin." (PMID 40822580, 2025). "Sepsis also triggers a massive release of pro-inflammatory cytokines, such as interleukin-6 (IL-6), tumor necrosis factor-alpha (TNF-α), and interleukin-1 beta (IL-1β), as well as reactive oxygen species (ROS)." (PMID 40563999, 2025). "Persistent inflammation post-sepsis, characterized by the sustained release of pro-tumorigenic cytokines like IL-6 and TNF-α, fuels tumor growth and immune evasion, increasing the risk of recurrence." (PMID 40563999, 2025). "As IL-6 is involved in the development of autoimmunity and plays a crucial role in sepsis, targeting the IL-6 axis is an approved pharmacological option in a number of autoimmune disorders." (PMID 40529825, 2025). "ILs such as IL-1β, IL-6, IL-12, IL-17 and IL-18 play a crucial role in sepsis-induced myocardial injury." (PMID 40520010, 2025). "The sensing system thus holds promise forclinical applications, providing rapid and accurate IL-6 monitoringfor sepsis patient care." (PMID 39907592, 2025). "High-dose levosimendan elicited a pronounced rise in IL-6 at the 5th hour, significantly higher than both the sham and sepsis control groups." (PMID 40566580, 2025). "TNF-α and IL-6, important pro-inflammatory cytokines, play a key role in the inflammatory cascade of sepsis." (PMID 41393152, 2025). "Pooled analysis showed that dexmedetomidine reduced the peripheral blood IL-6 level in sepsis patients [standardized mean difference (SMD) = −2.65, 95% confidence interval (95%CI) = (−2.65, −0.28), p = 0.028], and this difference was statistically significant." (PMID 41195185, 2025). "Interleukin-6 (IL-6), an inflammatory cytokine produced by immune cells as a response to infection and tissue damage, plays a key role in the pathogenesis of sepsis." (PMID 40149943, 2025). "A meta-analysis of clinical trials using DEX to treat sepsis patients in intensive care units (ICU) found that its use significantly reduced IL-6, TNF-α and overall mortality." (PMID 41124072, 2025). "Multiplex panels that combine biomarkers like NSE, IL-6, and PCT, paired with Artificial Intelligence will enhance diagnostic accuracy and predict outcomes in conditions like sepsis and ARDS." (PMID 40310334, 2025).
Sepsis (continued). "Published data demonstrate that interferon-γ–inducible chemokines, particularly CXCL9, are significantly higher in HLH compared with sepsis, whereas IL-6 is elevated in both conditions but typically reaches higher levels in sepsis." (PMID 41234904, 2025). "When implanted into the caudal vein of sepsis mice, the device stably monitors IL‐6 level and maintains reliable synaptic response to inflammatory‐triggered elevations." (PMID 40755409, 2025). "This is illustrated by the case (Circuit 11) of a patient who was treated with CytoSorb because of hemophagocytic syndrome, developed sepsis during treatment with CytoSorb, and had increasing IL-6 levels over time despite effective removal." (PMID 41140657, 2025). "Research has shown that ADAR1 targets miR-30a to regulate SOCS3 expression, thereby reducing IL-6 levels, mitigating inflammation and organ damage and providing protection against sepsis." (PMID 41306613, 2025). "IL-6 rises sharply within 2 to 3 h in response to endotoxin and declines rapidly within 8 h, making it a valuable early marker for sepsis detection." (PMID 40892314, 2025). "Based on these results, baseline IL-6 appears to have a moderate ability to predict mortality in sepsis patients." (PMID 40149943, 2025). "The SOFA and APACHE II scores, as well as lactate and IL-6 levels, were identified as prognostic factors in patients with sepsis." (PMID 40094854, 2025). "of sepsis induction revealed an exacerbated inflammatory response evidenced by increased tissue levels of proinflammatory cytokines IL‐6, IL‐1β and TNF‐α." (PMID 39444093, 2025). "IL-6 is a crucial mediator in the inflammatory response during sepsis, produced by various cells, including leukocytes and endothelial cells." (PMID 40497942, 2025). "While CRP, lactate, PCT, IL-6, and MR-proADM offer distinct advantages for predicting unfavorable short-term outcomes in sepsis, their comparative and/or combined effectiveness in predicting long-term mortality has yet to be fully explored." (PMID 40724799, 2025). "Experimental work with polyester-polymer-alloy (PEPA) prototypes shows two-fold greater IL-6 removal than cellulose triacetate in rat sepsis models, providing a platform for next-generation filters." (PMID 40868084, 2025). "Mechanistically, during the late immunosuppressive phase of sepsis, M2 macrophages are activated by Th2 cytokines (IL-4 and IL-13), LPS, glucocorticoids, IL-10, IL-6, or TGF-β." (PMID 40364841, 2025). "Combining IL-6 measurements with other biomarkers like PCT and CRP enhances diagnostic accuracy, particularly for conditions such as ARDS and sepsis." (PMID 40310334, 2025). "The ability of these factors, including plasma granzyme B, to predict 28-day mortality in patients with sepsis was statistically significant, except for IL-6." (PMID 40094854, 2025). "In a systematic review and meta-analysis, it was found that IRAK3 expression and its effect on inflammatory markers (TNF-α and IL-6) varied at different stages of sepsis, affected by changes in experimental procedures." (PMID 40108736, 2025). "In fact, treatment with recombinant sgp130Fc has shown superior results over global IL-6 signaling blockade in several disease models, such as myocardial infarction, sepsis, and acute pancreatitis." (PMID 38980514, 2025). "This study reveals the potential of multi-marker panels comprising admission-day levels of IL-6, PT-INR, and HDL to act as a powerful and synergistic early risk stratification tool in severe sepsis cases." (PMID 40959673, 2025). "This study investigated the therapeutic potential of optimized treatment timing in sepsis immunotherapy, with TCZ treatment administered at varying intervals, using IL-6 as a biomarker in LPS-induced sepsis rats." (PMID 39955435, 2025). "IL-6 emerges as a more reliable biomarker for the early detection of sepsis due to its high sensitivity and good specificity." (PMID 40242671, 2025).
Sepsis (continued). "IL-6 independently predicts sepsis with moderate sensitivity and relatively high specificity, supporting its potential as a complementary marker in early diagnosis." (PMID 41011807, 2025). "We assessed IL-6's ability to differentiate between late-onset sepsis (LOS) and NEC and between medical and surgical NEC." (PMID 39958363, 2025). "A recent clinical trial has shown that using the “our Methods”significantly restores levels of cTnI and pro-BNP in sepsis patients, reduce levels of inflammatory factors such as IL-6 and IL-10, and improve heart function." (PMID 40520010, 2025). "IL-6 levels in neutropenic patients experiencing a strong inflammatory stimulus, i.e., sepsis, were 20,659 pg/mL (IQR 4225–170,288) compared to 533 pg/mL (IQR 140–1978) in non-neutropenic patients." (PMID 41155261, 2025). "Biomarkers have shown significant promise in prognostication following acute respiratory distress syndrome (ARDS) and sepsis: interleukin (IL)-6, IL-8 (otherwise known as C-X-C motif ligand-8 or CXCL8), and tumor necrosis factor receptor 1 (TNFR1)." (PMID 40433392, 2025). "IL-6 levels were substantially elevated in sepsis (median 1150 pg/mL) and neutropenia (median 7866 pg/mL), with extreme concentrations exceeding 20,000 pg/mL when both were present." (PMID 41155261, 2025). "This narrative review aims to synthesize current evidence on the predictive value of umbilical cord blood IL-6 for neonatal outcome, including sepsis, respiratory distress, hypoxic–ischemic encephalopathy (HIE) and mortality." (PMID 41302151, 2025). "In sepsis, IL-6 occupies a central position during both early and late phases of the immune response." (PMID 41300951, 2025). "Previous sepsis research has largely focused on traditional biomarkers such as procalcitonin, C-reactive protein, IL-6, and TNF-α, which are critical mediators of the early inflammatory response." (PMID 40230692, 2025). "The results showed that APACHE II, WBC, PCT, CRP, TNF-α, IL-6, and SOFA scores were the independent risk factors for the 28-day survival of patients with sepsis after high-dose CRRT (all p < 0.05)." (PMID 41393152, 2025). "Firstly, despite including a substantial number of studies that investigated the role of IL-6 in sepsis prognosis, there was a limited number of studies that reported the dynamic changes in plasma IL-6 over time." (PMID 40149943, 2025). "Although variability in study design and sepsis definitions existed, the overall evidence supports IL-6 as one of the most promising standalone biomarkers currently available." (PMID 41302151, 2025). "In prolonged sepsis, cardiac expression of IL-1β and IL-6 and macrophage infiltration remained upregulated (p ≤ 0.05)." (PMID 39821755, 2025). "Promising experimental evidence has shown that curcumin protects cardiomyocytes from sepsis-induced injury by activating the Nrf2/HO-1 pathway, mitigating ferroptosis, and attenuating the IL-6 and IL-1β response to LPS stimulation." (PMID 41300951, 2025). "With regards to the role of IL-6 in human diseases, it is notable that blood levels of IL-6 in a healthy human is 1-5 pg/ml and can increase to 1000 folds in some inflammatory conditions and up to several μg/ml during sepsis." (PMID 40114923, 2025). "IL-6 levels were 1.61 pg/mL in the sham group, 3.51 pg/mL in the sepsis group, 1.83 pg/mL in the pre-sepsis pomegranate group, and 1.63 pg/mL in the post-sepsis pomegranate group (p = 0.180)." (PMID 40896042, 2025). "2DG and oxamate also mitigated sepsis‐induced lung tissue injury as well as systemic proinflammatory responses as represented by decreased plasma levels of cytokine IL‐6 and TNFα." (PMID 39822760, 2025). "In our study, IL-6 levels were significantly elevated (p < 0.01) in the sepsis groups compared to controls." (PMID 41517447, 2025). "IL-6 has, up till now, been researched in both sepsis and acute kidney injury, in various in vitro, animal, and human studies, in children and adults." (PMID 40142279, 2025).